MYL12A (myosin light chain 12A)
Description:
Myosin regulatory subunit that plays an important role in regulation of both smooth muscle and nonmuscle cell contractile activity via its phosphorylation. Implicated in cytokinesis, receptor capping, and cell locomotion (By similarity).
Synonyms: HEL-S-24; MLCB; MRLC3; MYL2B; MRCL3; MLC-2B
Tractability: PROTAC: ubiquitination databases record sites on it; its protein half-life has been measured.
Gene: Protein-coding gene on chromosome 18 (3,247,481 to 3,256,260, forward strand). Ensembl gene ENSG00000101608.
Pathways (Reactome):
Developmental Biology: Ephrin signaling
Muscle contraction: Smooth Muscle Contraction
Gene Ontology:
Molecular function: protein binding; myosin heavy chain binding; calcium ion binding
Biological process: platelet aggregation
Cellular component: extracellular exosome; cytoplasm; cytosol; myosin II complex
Genetic constraint (gnomAD): Loss-of-function variants: 11 observed, 13.57 expected, observed/expected ratio (o/e) 0.81, 90% interval 0.51 to 1.34. The synonymous counts are far from expectation, so gnomAD's model fits this gene poorly and the ratio says little. Missense variants: 146 observed, 215.54 expected, observed/expected ratio (o/e) 0.68, 90% interval 0.59 to 0.78. Synonymous variants: 51 observed, 71.99 expected, observed/expected ratio (o/e) 0.71, 90% interval 0.56 to 0.89.
Homologues: Orthologues: chimpanzee MYL12A (100% identical), dog MYL12A (99% identical), pig MYL12A (99% identical), guinea pig MYL12A (99% identical), mouse Myl12a (98% identical), rat Myl12a (98% identical), tropical clawed frog myl12b (96% identical), zebrafish myl12.2 (95% identical), macaque MYL12B (70% identical), Caenorhabditis elegans mlc-1 (49% identical), Caenorhabditis elegans mlc-2 (49% identical). Paralogues in human: MYL12B (98% identical), MYL9 (94% identical), MYL2 (56% identical), MYL11 (56% identical), MYL5 (55% identical), MYL10 (54% identical), MYL7 (50% identical).
Diseases named in the same sentence as MYL12A in open-access papers:
MYL12A is named in the same sentence as 15 diseases in open-access papers, as found by Europe PMC text mining. Sharing a sentence is not in itself a finding about the gene and the disease. The quoted sentences say what the papers report.
Salmonella Infections (2 papers, 2023 to 2024). Infections with bacteria of the genus SALMONELLA. "Moreover, the phosphorylation of Myl12a was detected in BMDM cells as early as 15 min after wild-type Salmonella infection." (PMID 38528181, 2024).
bipolar disorder (1 paper, 2015). A disorder of the brain that causes unusual shifts in mood, energy, activity levels and the ability to carry out day-to-day tasks. "The result showed that 6 genes (including MAD1L1, JAM3, MYL12B, MYL12A, ITIH1 and RYR2) had been reported to be significant associated with bipolar disorder in at least one genetic study." (PMID 26193471, 2015).
co-infection (1 paper, 2015). "MYL12A is involved in the regulation of the actin cytoskeleton and is found to be upregulated in HIV/HCV co-infection." (PMID 26426037, 2015).
colitis (1 paper, 2020). Inflammation of the colon. "To this end, we used a DSS-induced colitis model, which was established by treating wild-type C57BL/6 mice with 2% DSS, which was administered in their drinking water for 7 days, and used an antibody that can detect Myl9, Myl12a, and Myl12b." (PMID 33584659, 2020).
infection (3 papers, 2015 to 2024). The state of being infected such as from the introduction of a foreign agent such as serum, vaccine, antigenic substance or organism. "However, its parent gene MYL12A shows modulating gene expression at 12 h and 24 h post-infection." (PMID 26426037, 2015). "The topological plots showed that GNA13 and ARHGEF12 were significantly downregulated at 48 h post-infection, and these genes inhibit the Calcium signaling pathway by regulating ROCK1 and MYL12A." (PMID 37211158, 2023). "We found that genes of the Calcium signaling pathway were all significantly downregulated at 24 and 48 h post-infection, such as GNA13, ARGHGEF12, ROHA, ROCK1, and MYL12A." (PMID 37211158, 2023). "The results showed that phosphorylation of Myl12a was dramatically upregulated in WT-infected cells 1 h post-infection, whereas no phosphorylation of Myl12a was detected in the ΔsteC-infected cells." (PMID 38528181, 2024).
cancer (1 paper, 2011). A tumor composed of atypical neoplastic, often pleomorphic cells that invade other tissues. "Notably, IPA analysis identified 12 of the ERβ-interacting proteins as having roles in cancer progression and metastasis with 4 of these proteins having established roles in NSCLC, i.e., EEFIA, MYL12A, TUBB2A, VIM1." (PMID 21951318, 2011).
tumor (1 paper, 2024). "Patient-derived protein data revealed that OTUD3 is highly expressed in DLBCL tumor tissues and is associated with elevated levels of MYL12A and PD-L1." (PMID 39097608, 2024). "In summary, OTUD3 modulates MYL12A stability, enhancing DLBCL survival and metastasis, and stabilizes PD-L1, promoting CD8+ T cell exhaustion and dampening tumor immunity." (PMID 39097608, 2024).
MYL12A also shares sentences with these, for which no sentence is quoted: acute respiratory distress syndrome (1 paper); atherosclerosis (1); breast carcinoma (1); colorectal tumour (1); glioma (1); melanoma (1); myopia (1); tuberculosis (1).